KDM1A (lysine demethylase 1A)
Diseases named in the same sentence as KDM1A in open-access papers (continued):
Sharing a sentence is not in itself a finding about the gene and the disease.
cervical carcinoma (14 papers, 2008 to 2025). A carcinoma arising from either the exocervical squamous epithelium or the endocervical glandular epithelium. "Taking above information together, we hypothesized that KDM1A may also be implicated in cervical cancer development by regulation on certain gene expression through acetylation or deacetylation." (PMID 34350095, 2021). "The novelty of this study was KDM1A-mediated histone 3 deacetylation on regulation of DACT1 in cervical cancer." (PMID 34350095, 2021). "More importantly, we further explored the mechanism of KDM1A regulation on DACT1 in cervical cancer." (PMID 34350095, 2021). "Further exploration on KDM1A regulation on biological function of cervical cancer cells in this study showed that KDM1A can induce histone 3 deacetylation so as to suppress the expression of DACT1." (PMID 34350095, 2021). "The collected evidence showed that KDM1A in cervical cancer cells can suppress the expression of DACT1 through histone 3 deacetylation and therefore enhance the progression of this disease." (PMID 34350095, 2021). "This study is aimed at exploring the mechanism behind the KDM1A regulation on DACT1 in cervical cancer cells." (PMID 34350095, 2021). "Further investigation in cervical cancer cell lines confirmed the highly expressed profile of KDM1A in cervical cell lines and also identified DACT1 as a target gene of KDM1A." (PMID 34350095, 2021). "Typical searching in TCGA database identified that KDM1A was highly expressed in cervical cancer tissues." (PMID 34350095, 2021). "Consistently, with a previous literature, this study demonstrated KDM1A is highly expressed in both cervical cancer tissues and cell lines, whose suppression contributed greatly to the suppression on cell proliferation and migration of cervical cancer cells." (PMID 34350095, 2021). "To explore the effect of KDM1A on cervical cancer cells, we planned to transfect sh-KDM1A into HeLa and SiHa cells to achieve KDM1A suppression." (PMID 34350095, 2021). "Taken together, KDM1A enhances the proliferation and migration of cervical cancer cells through regulating the expression of DACT1." (PMID 34350095, 2021). "In summary, results in this study showed that KDM1A was highly expressed while DACT1 was lowly expressed in cervical cancer tissues and cells." (PMID 34350095, 2021). "KDM1A could downregulate DACT1 expression through histone deacetylation to enhance the proliferation of cervical cancer cells." (PMID 35864965, 2022). "But the implication of KDM1A in cervical cancer is not fully understood." (PMID 34350095, 2021). "Therefore, KDM1A enhances the progression of cervical cancer by inducing histone 3 deacetylation and downregulating DACT1 expression." (PMID 34350095, 2021). "Therefore, KDM1A may be able to regulate DACT1 expression through histone 3 deacetylation in cervical cancer cell lines." (PMID 34350095, 2021). "Therefore, this study was performed to verify whether KDM1A can regulate DACT1 expression to regulate biological functions of cervical cancer cells." (PMID 34350095, 2021). "The measurement on cell proliferation and migration ability showed that overexpression of DACT1 could suppress cell proliferation and migration of cervical cancer cells, while overexpression of KDM1A could abolish DACT1-mediated suppression on cervical cancer cells." (PMID 34350095, 2021). "Thereafter, we measured the mRNA and protein expression levels of KDM1A and DACT1 in cervical cancer cell lines (HeLa, Ca Ski, SiHa, and C-33A) and immortalized human cervical epithelial cell line H8." (PMID 34350095, 2021). "TCGA database showed that cervical cancer tissues had elevated expression of KDM1A and decreased expression of DACT1, which was consistent with the observation in cervical cancer cell lines." (PMID 34350095, 2021). "The results showed that KDM1A was highly expressed and DACT1 (305/3) was lowly expressed in cervical cancer tissues (p < 0.01)." (PMID 34350095, 2021).
cervical carcinoma (continued). "In vitro experiments verified the effect of KDM1A and DACT1 on proliferation and migration ability of cervical cancer cell lines after cell transfection." (PMID 34350095, 2021). "KDM1A can lead to histone 3 deacetylation, which consequently represses the expression of DACT1 in cervical cancer cells." (PMID 34350095, 2021). "In this study, we demonstrated the increased expression level of KDM1A and decreased expression level of DACT1 in both cervical cancer tissues (from TCGA database) and cervical cell lines." (PMID 34350095, 2021). "qRT-PCR and western blot demonstrated that compared with H8 cells, the mRNA (p < 0.01) and protein (p < 0.01) expressions of KDM1A were elevated, while those of DACT1 were decreased (p < 0.01) in all cervical cancer cell lines." (PMID 34350095, 2021). "To further identify the possible interaction between KDM1A and DACT1 in cervical cancer cell lines, we then cotransfected overexpression of KDM1A and DACT1 in cervical cancer cell lines." (PMID 34350095, 2021). "KDM1A can downregulate DACT1 expression through histone deacetylation and therefore suppress the proliferation and migration of cervical cancer cells." (PMID 34350095, 2021). "Increased expression of KDM1A and decreased expression of DACT1 in cervical cancer cells were noticed in a previous study." (PMID 34350095, 2021). "The expression levels of KDM1A and DACT1 in cervical cancer cell lines were determined by qRT-PCR and western blot." (PMID 34350095, 2021). "The expression profile of KDM1A and DACT1 in cervical cancer tissues was searched in TCGA database." (PMID 34350095, 2021). "Interaction between the KDM1A and DNMT proteins was also shown in HeLa cervical carcinoma cells." (PMID 27449289, 2016). "Therefore, we speculated that KDM1A may be able to downregulate DACT1 expression through histone deacetylation, to enhance the proliferation and migration of cervical cancer cells." (PMID 34350095, 2021).
diabetes (13 papers, 2014 to 2025). "KDM1A was associated with seven drugs, and MAOA with six drugs, many of which were monoamine oxidase inhibitors prescribed for depression and hypertension or PPAR stimulators used in diabetes treatment." (PMID 37958805, 2023).
Alzheimer disease (12 papers, 2017 to 2025). A progressive, neurodegenerative disease characterized by loss of function and death of nerve cells in several areas of the brain leading to loss of cognitive function such as memory and language. "It has been reported that KDM1A-mediated upregulation of METTL3 ameliorates Alzheimer's disease." (PMID 39800682, 2025). "Recently it could be demonstrated that inhibition of KDM1A corrects memory deficit and behavior alterations in a mouse model of Alzheimer’s Disease." (PMID 35802656, 2022). "Regarding lysine demethylases, inhibitors of KDM1A are in clinical trials for refractory cancers and Alzheimer’s disease, while inhibitors of KDM4 and KDM4C are only being studied for refractory cancers, and drug discovery in this field may be realized in the near future." (PMID 36975603, 2023). "ORY-2001 efficiently inhibits brain KDM1A at doses suitable for long term treatment, and corrects memory deficit as assessed in the novel object recognition testing in the Senescence Accelerated Mouse Prone 8 (SAMP8) model for accelerated aging and Alzheimer’s disease." (PMID 32469975, 2020).
lung adenocarcinoma (12 papers, 2015 to 2026). A carcinoma that arises from the lung and is characterized by the presence of malignant glandular epithelial cells. "The co-expressed genes of KDM1A were downloaded from a lung adenocarcinoma dataset, TCGA Pan-Cancer Atlas, to further evaluate the underlying mechanisms regulated by KDM1A co-expression molecules." (PMID 36357457, 2022). "To examine the expression pattern of KDM1A in NSCLC patients, we analyzed the gene expression data from lung adenocarcinoma in the TCGA database." (PMID 27058897, 2016). "However, non-synonymous mutations in KDM1A in human lung adenocarcinoma are as rare (0.53% in TCGA PanCancer Atlas) as CLCC1, suggesting that CLCC1 and KDM1A are not mutational drivers in this disease." (PMID 34779486, 2022).
lymphoma (12 papers, 2013 to 2026). A malignant (clonal) proliferation of B- lymphocytes or T- lymphocytes which involves the lymph nodes, bone marrow and/or extranodal sites. "We summarize the current state of development for inhibitors against Menin‐KMT2A, DOT1L, KDM1A, and Polycomb complexes, and the arginine methyltransferase PRMT5 for the treatment of myeloid malignancies, lymphoma, and different solid tumors." (PMID 40181550, 2026).
Obesity (11 papers, 2017 to 2024). Accumulation of substantial excess body fat. "Additionally, this EVOO-related secoiridoid has been shown to inhibit lysine-specific histone demethylase 1A (LSD1) also known as lysine (K)-specific demethylase 1A (KDM1A) a central epigenetic regulator of metabolic reprogramming in obesity-associated diseases, neurological disorders, and cancer." (PMID 36355509, 2022). "Strikingly, GWAS studies have previously highlighted SNPs associated to phenotypes linked to inflammation and/or obesity, such as BMI and waist to hip ratio in humans for SMYD3, ELP6 and KDM1A." (PMID 38148333, 2024). "Of note, dietary-induced and genetic mouse models of obesity display a decreased level of KDM1A (Lysine Demethylase 1A), a histone demethylase, in AT, which correlates with an increased expression of pro-inflammatory genes." (PMID 35883538, 2022).
oral cancer (10 papers, 2017 to 2023). "A study found that overexpression of KDM1A induces E2F1 signaling via histone demethylation and promotes cell proliferation in oral cancer and that inhibition of KDM1A reduces E2F1 signaling, implying an oncogenic role of KDM1A in oral cancer." (PMID 34220955, 2021). "Oral cancer is the most common cancer among developing countries, and KDM1A expression is upregulated in oral tumors compared to levels in normal oral tissues." (PMID 29921310, 2018). "KDM1A regulates the E2F1 signaling pathway in oral cancer and increases cell proliferation." (PMID 29921310, 2018).
endometrial cancer (9 papers, 2014 to 2023). Primary or metastatic malignant neoplasm involving the endometrium (mucous membrane that lines the endometrial cavity). "In the treatment of endometrial cancer, combined with mTOR inhibitors, KDM1A inhibitors were found to inhibit tumor growth in ex vivo and in vivo experiments." (PMID 36742386, 2023).
lymph node metastasis (8 papers, 2015 to 2022). "Multivariate logistic analysis of lymph node metastasis and clinicopathological features showed that KDM1A expression, age and BRAF mutation were independent prognostic factors for lymph node metastasis in PTC." (PMID 35198054, 2022). "As shown in, KDM1A positive expression was significantly related to age <55 years (P = 0.019) and lymph node metastasis (P = 0.035)." (PMID 31211500, 2019). "In conclusion, we have identified KDM1A as a metastasis promoter in PTC and that it is associated with lymph node metastasis." (PMID 31211500, 2019). "As shown in, PTC tissues had significantly elevated KDM1A protein levels, especially in tissue from patients with lymph node metastasis." (PMID 31211500, 2019). "High KDM1A expression correlated positively with age <55 years and lymph node metastasis in patients with PTC." (PMID 31211500, 2019).
brain tumors (7 papers, 2013 to 2025). "Notably, inhibition of KDM1A and HDAC turned out to have synergistic effects inhibiting tumor development in other types of brain tumors." (PMID 24252778, 2013).
depression (7 papers, 2018 to 2025). "Methylation analyses of 9 promoter/regulatory regions of genes known to be implicated in depression/PTSD (ADCYAP1, BDNF, CRHR1, DRD2, IGF2, LSD1/KDM1A, NR3C1, OXTR, SLC6A4) were performed on DNA from blood samples by the MassARRAY EpiTYPER platform, with MassCleave settings." (PMID 36001138, 2023). "However, the KDM1A inhibitor, tranylcypromine (TCP), is in clinical use as a monoamine oxidase (MAO) inhibitor to treat therapy-resistant depression." (PMID 34771652, 2021).
Kabuki syndrome (7 papers, 2019 to 2025). Kabuki syndrome (KS) is a multiple congenital anomaly syndrome characterized by typical facial features, skeletal anomalies, mild to moderate intellectual disability and postnatal growth deficiency. "Humans with mutations in KDM1A are reported to have craniofacial defects including cleft palate and developmental delay; these clinical features are also found in Kabuki syndrome." (PMID 33954026, 2021). "Furthermore, one patient with KGB syndrome and Kabuki syndrome has been reported to have a de novo missense mutation of KDM1A, along with a de novo 3-bp deletion of another gene, ANKRD11." (PMID 31649809, 2019). "Recent studies have shown that upregulation of H3K4 methylation by oral KDM1A-specific inhibitors can rescues the defects of adult neurogenesis in the mouse models of Kabuki syndrome (KS), significantly improve the visuospatial learning and memory defect." (PMID 39664113, 2024). "Lysine-specific histone demethylase 1A (KDM1A; alias: LSD1) is primarily described as a H3K4me1 and me2 demethylase implicated in phenotypes of cognitive impairment that resemble Kabuki syndrome (OMIM: 147920)." (PMID 30832413, 2019). "In addition, the KDM1A/LSD1 inhibitor TAK-418 has been tested for tolerability, pharmacokinetics and pharmacodynamics in Kabuki syndrome patients with promising results." (PMID 39680066, 2024). "LSD1, also known as lysine demethylase 1A (KDM1A), is a histone demethylase which has been reported to suppress H3K4me1 and H3K4me3 modifications and inhibit neurogenesis and impair hippocampal memory in a mouse model of Kabuki syndrome." (PMID 35592894, 2022).
myelofibrosis (7 papers, 2019 to 2024). A partial or complete replacement of the bone marrow stroma by fibrous tissue. "Thirdly, outside oncology, LSD1/KDM1A is an enzyme of interest to treat pathologies such as myelofibrosis, autism and other diseases." (PMID 36840175, 2023). "In this review, the role of LSD1/KDM1A inhibition as a potential disease-modification strategy in patients with myelofibrosis is described and discussed." (PMID 35805191, 2022). "In this review, the role of LSD1/KDM1A inhibition as a potential disease-modification strategy in patients with myelofibrosis is appraised." (PMID 35805191, 2022).
sarcoma (7 papers, 2016 to 2025). A usually aggressive malignant neoplasm of the soft tissue or bone. "Histone demethylases such as KDM1A (LSD1) are also overexpressed in many childhood sarcoma types, resulting in loss of methylation at H3K4 and transcriptional activation of oncogenic signalling." (PMID 40983796, 2025). "SP-2577 (seclidemstat), a selective inhibitor of KDM1A, demonstrated in vivo efficacy in a variety of paediatric sarcomas." (PMID 40983796, 2025).
schizophrenia (7 papers, 2017 to 2025). A major psychotic disorder characterized by abnormalities in the perception or expression of reality. "Moreover, the role of KDM1A in schizophrenia is the rationale for EVOLUTION, an adaptive double‐blind placebo‐controlled phase IIb trial in schizophrenia, with multiple end points including improvement in negative symptoms and in cognitive impairment associated with schizophrenia." (PMID 39936839, 2025).
esophageal cancer (6 papers, 2017 to 2023). A primary or metastatic malignant neoplasm involving the esophagus. "In vitro experiments with oesophageal cancer cell lines focusing on the study of HDM have shown a decrease in the migration and invasion capabilities of cancer cells upon KDM1A silencing." (PMID 32429269, 2020). "In colon adenocarcinoma (COAD), rectum adenocarcinoma (READ), stomach adenocarcinoma (STAD), and esophageal carcinoma (ESCA), KDM1A expression was upregulated in cancer tissues, compared with that in NATs, and slight difference was observed among different stages of cancers." (PMID 37250145, 2023).
multiple myeloma (6 papers, 2019 to 2025). "Continuing with the epigenetic theme, WES recently identified in a pedigree of early-onset myeloma the first autosomal-dominant MM predisposition gene: germline N-terminal truncating mutations in LSD1 (lysine demethylase 1A, official gene symbol KDM1A)." (PMID 31139207, 2019). "Furthermore, genetic susceptibility was indicated in ALL and multiple myeloma, with constitutional mutations in genes such as IKZF1, SH2B3, PAX5 (ALL) and KDM1A/LSD1 (multiple myeloma)." (PMID 36998465, 2023). "Notably, such models have been used to dissect epigenetic mechanisms of pathogenesis, including the role of histone demethylase LSD1/KDM1A, whose dysregulated activity contributes to aberrant transcriptional programs and targetable vulnerabilities in myeloma." (PMID 41346447, 2025).
ovarian tumors (6 papers, 2013 to 2024). "Lysine-specific demethylase 1 (LSD1/KDM1A) acts as an epigenetic regulator and is overexpressed in ovarian tumors." (PMID 26489763, 2015).
acute leukemia (5 papers, 2016 to 2021). A clonal (malignant) hematopoietic disorder with an acute onset, affecting the bone marrow and the peripheral blood. "ORY-1001 was identified as a potent and selective covalent inhibitor of KDM1A for the inhibition cell proliferation of acute leukemia." (PMID 30568590, 2018). "ORY-1001, an inhibitor of covalent lysine (K)-specific demethylase 1A (KDM1A), has been used as a therapy for the treatment of acute leukemia." (PMID 30568590, 2018).